TLR9 (toll like receptor 9)
Diseases named in the same sentence as TLR9 in open-access papers (continued):
Sharing a sentence is not in itself a finding about the gene and the disease.
dengue (9 papers, 2013 to 2025). "The present study demonstrates that mutants of TLR3 rs3775291 and heterozygous genotypes of TLR7 and TLR9 are associated with susceptibility of dengue virus infection." (PMID 34113509, 2021). "Mutant allele of TLR7 and TLR9 was significantly associated with dengue." (PMID 34113509, 2021). "In the present study, heterozygous genotypes of TLR9 (rs187084, rs5743836) and of TLR7 (rs179008, rs179009) were found to be significantly associated with dengue cases as compared to controls." (PMID 34113509, 2021). "It remains to be investigated if this is due to lower expression of TLR9 in B cells from dengue patients or if DENV interferes with the TLR signaling pathway in B cells." (PMID 34293057, 2021). "Increased TLR3 and TLR9 expression was found in DCs of patients with dengue fever (DF) early in infection, and poor stimulation of TLR3 and TLR9 was observed in DCs from patients with severe manifestations, suggesting a role for TLRs in dengue pathogenesis." (PMID 34603272, 2021). "However, when stimulated with CpG in conjunction with BCR ligation, these cells showed an activated phenotype, showing that B cells from dengue patients are refractory to sole TLR9 stimulation." (PMID 34293057, 2021). "However, previously we reported that myeloid DCs of dengue infected patients have an increased expression of TLR9 compared to healthy controls." (PMID 34634046, 2021). "Therefore, we evaluated the expression levels of TLR2, TLR3, TLR4 and TLR9 in mDCs, pDCs and monocytes of dengue patients, and compared them to the HCs." (PMID 23469297, 2013). "Increased expression of TLR3 and TLR9 in DCs of patients with dengue fever (DF) early in infection was detected." (PMID 23469297, 2013). "Therefore, to assess whether the CpG ODN that triggers human TLR9 signalling can accelerate dengue clearance, we collected the supernatant of human PBMC for 3 days with CpG ODN type K or type D, and then overlayed the resulting supernatants on infected VERO E6 cells." (PMID 40059770, 2025). "A link between TLRs expression and the severity of dengue was observed: patients with dengue fever express higher levels of TLR3 and TLR9 than patients with DHF." (PMID 23469297, 2013). "Taken together, these findings suggest that the regulation of TLR9 signaling by miRNA-574-5p and FOXN3 might have an impact on the development of severe dengue and deserves further study to clarify this relationship." (PMID 36251659, 2022). "When stimulated with TLR9 agonist CpG, we have shown that activation markers CD69 and CD86 were not up-regulated and that no secretion of IL-10 and TNF-α was observed in B cells from dengue patients compared to healthy donors." (PMID 34293057, 2021). "B cells isolated from dengue patients were refractory to TLR9 stimulation, as we did not observe an upregulation of activation markers or co-stimulatory markers required for antigen presentation in naïve B cells after in vitro stimulation." (PMID 31736948, 2019). "In mDCs of dengue patients, TLR3, TLR4 and TLR9 reached maximum expression on day 5 of illness." (PMID 23469297, 2013).
endothelial dysfunction (9 papers, 2017 to 2026). In vascular diseases, endothelial dysfunction is a systemic pathological state of the endothelium (the inner lining of blood vessels) and can be broadly defined as an imbalance between vasodilating and vasoconstricting substances produced by (or acting on) the endothelium. "Circulating mtDNA fragments, acting as DAMPs, can activate TLR9 and fuel systemic inflammation, a pathway implicated in myocardial injury and endothelial dysfunction." (PMID 40429707, 2025). "Circulating mtDNA has been shown to act as a damage-associated molecular pattern (DAMP), activating Toll-like receptor 9 (TLR9) signaling and exacerbating endothelial dysfunction and cardiac fibrosis." (PMID 40429707, 2025). "Both probiotics prevented hypertension and endothelial dysfunction, reduced the plasma levels of autoantibodies against double-stranded DNA, activated Toll-like receptor 9 (TLR-9) expression, and reduced T-cell activation." (PMID 37432320, 2023). "Released during necrosis, apoptosis, and neutrophil extracellular trap (NET) formation, histones act as damage-associated molecular patterns (DAMPs), engaging receptors such as Toll-like receptors (TLR2, TLR4, TLR9) to trigger endothelial dysfunction, platelet activation, and cytokine release." (PMID 41993174, 2026). "In addition to serving as a marker, mt-cfDNA may contribute to endothelial dysfunction and sustain ongoing inflammation through activation of Toll-like receptor 9 (TLR-9) pathway." (PMID 38132094, 2023). "Further on, neutrophil TLR9 expression showed significant negative correlation with sCD141 at day 1 and day 8 after surgery, arguing for a protective role of TLR9 on endothelial dysfunction." (PMID 29234042, 2017).
gastritis (9 papers, 2012 to 2025). Inflammation of the stomach. "In vivo, recognition of H. pylori by TLR9 can lead to a pro-inflammatory response, and conversely, TLR9 can promote anti-inflammatory signaling, thus acting as an inhibitor of H. pylori-induced gastritis and establishing persistent infection." (PMID 40083792, 2025). "In a recent report, TLR9−/− mice were found to show increased signs of gastritis upon H. pylori infection." (PMID 32184393, 2020). "Further, a study using a murine model of H. pylori infection has suggested that TLR9 signaling is involved in the suppression of H. pylori-induced gastritis in the early phase of infection via down-regulation of Th1-type cytokines modulated by IFN-α." (PMID 25101079, 2014). "While TLR2, TLR4, TLR5, and TLR9 appear to be important for H. pylori recognition, their role in the evolution of gastritis to more advanced lesions remains unclear." (PMID 25101079, 2014). "Using confocal microscopy, TLR4, TLR5 and TLR9 have been observed in the antrum and corpus of the stomach samples from patients with H. pylori-related gastritis and with non-inflamed gastric mucosa." (PMID 40362298, 2025).
hepatitis B (9 papers, 2018 to 2025). "CpG oligonucleotide (ODN), a kind of Toll-like receptor 9 (TLR9) agonist, proves to be a safe and promising adjuvant for the development of new-generation vaccines and has been used in an approved recombinant hepatitis B vaccine (HEPLISAV-B®)." (PMID 40487171, 2025). "As is known, CpG is a TLR9 agonist and has been successfully used as an adjuvant in commercial hepatitis B vaccines (e.g., HEPLISAV-B®)." (PMID 35493470, 2022). "To investigate the effect of TLR9 expression on the pathogenesis of hepatitis B, we first explored the relative expression of TLR9 mRNA in healthy volunteers, HBV-infected patients, and patients treated with entecavir and thymosin a1." (PMID 36596032, 2022). "One interesting finding of our study was that the co-culture of HepG2.215 and dendritic cells activated TLR9/STAT3 signaling and the expression level of TLR9 was positively correlated with HBV DNA in PBMCs from hepatitis B patients." (PMID 30202418, 2018). "In this study, the RBD-VLP antigen was formulated with two adjuvants: (i) aluminum hydroxide (alum) and (ii) alum combined with CpG 1018—a potent Toll-like receptor 9–agonizing adjuvant known to elicit T helper cell 1 (TH1)–like responses and used in the commercial hepatitis B vaccine, HEPLISAV-B." (PMID 35294244, 2022).
leishmaniasis (9 papers, 2014 to 2023). Infectious disease that is transmitted through the bite of hematophagous female phlebotomine sand flies. "In a mouse model, deletion of both TLR9 and MyD88 promoted lesion progression and increased levels of Th2-associated cytokines (IL-4 and IL-13) in leishmaniasis, which suggests that TLR9 and MyD88 play crucial roles in the Th1-mediated healing response against L. guyanensis." (PMID 36633419, 2023). "Our study indicates that TLR9 is associated with the mechanism of protection of intranasal LaAg vaccine and suggests that the use of a TLR9 agonist could be considered an adjuvant by intranasal route against leishmaniasis." (PMID 30802247, 2019). "In contrast, live attenuated LdCen−/− vaccine inherently elevates TLR-9 expression, eliminating the need for adjuvants and making it a more affordable option for vaccine formulation against different types of leishmaniasis." (PMID 37111420, 2023). "It has been reported previously that combination therapy of paromomomycin/miltefosine can influence TLR9 on dendritic cells and therefore modulate Th1 host immune responses in leishmaniasis therapy." (PMID 33450054, 2021). "Murine models of leishmaniasis have linked various TLRs (TLR2, TLR3, TLR4 and TLR9) with enhanced IFN-γ and IL-12 production and parasite control." (PMID 25397678, 2014). "We have shown that combining TLR4 and TLR9 agonists enhanced the efficacy of a therapeutic vaccine against Leishmaniasis." (PMID 24404140, 2014). "In our own work we have shown that combining MPLA or GLA with a TLR9 agonist CpG enhances the efficacy of a candidate therapeutic vaccine against Leishmaniasis." (PMID 24404140, 2014). "Early studies concluded that TLR2, TLR4, and TLR9, are involved in the recognition of L. major and that TLR2 ligands play a protective immune role against Leishmaniasis." (PMID 30462645, 2018). "Although some studies investigate the profile of the immune response during vaccination against leishmaniasis, this is mainly focused on IFN-γ and iNOS, and few studies investigate the participation of receptors, specially TLR9, in vaccination mechanisms against leishmaniasis." (PMID 30802247, 2019). "Most studies of TLRs in leishmaniasis have been done in the murine models, where expression of TLR2, TLR4, TLR7, TLR8 and TLR9 have been analyzed and related to disease outcome, together with other contributing factors such as Leishmania species and genetic background." (PMID 25397678, 2014).
liver diseases (9 papers, 2011 to 2025). "The role of tlr-9 gene in liver disease has been also investigated, and it has been found that tlr-9-defective mice are resistant to alcoholic fatty liver disease." (PMID 35165344, 2022). "In liver injuries, hepatocytes can release dsDNA, and TLR9 sustains liver diseases due to the recognition of extracellular DNA after necrotic cell death." (PMID 28530246, 2017). "From these studies, we know that TLR2, TLR7 and TLR9 play key roles in liver diseases and TLR2 has an potential function in the regulation of tumor tolerance, cancer progression and metastasis." (PMID 22815694, 2012). "DNA fragment-induced TLR9 activation might be an important driver of inflammatory responses in this widespread liver disease." (PMID 36176986, 2022). "Previous studies have shown that TLR9-driven response may lead to differential impact on the pathogenesis of liver diseases." (PMID 34262465, 2021). "TLR9 pathways are involved in the modulation of liver diseases." (PMID 24340043, 2013).
myocardial ischemia (9 papers, 2013 to 2023). A disorder of cardiac function caused by insufficient blood flow to the muscle tissue of the heart. "Yet, another study in experimental myocardial infarction has shown p38 MAPK activation in response to TLR9 aggravated myocardial ischemia-perfusion injury." (PMID 37212886, 2023). "The functional role of TLR9 in ischemic injury is controversial, with some studies in experimental stroke, and myocardial ischemia models have suggested a protective function of TLR9 through the PI3K/Akt signaling pathway." (PMID 37212886, 2023). "We hypothesized that hydroxychloroquine (HCQ) attenuates myocardial ischemia/reperfusion injury (IRI) via TLR9 – type I interferon (IFN-I) pathway inhibition." (PMID 36081846, 2022). "However, a study has shown the activation of the p38MAPK signaling pathway in response to the TLR9 activation aggravates myocardial ischemia-reperfusion injury." (PMID 33643304, 2020). "The role of TLR9 in cerebral and myocardial ischemia needs further studies as some groups have shown its activation has a protective action through activating PI3K/Akt signaling pathway during cerebral-ischemia reperfusion injury and myocardial-ischemia reperfusion injury in mice." (PMID 33643304, 2020). "The aim of this study was to elucidate the role of TLR9 in myocardial ischemia/reperfusion injury." (PMID 31160091, 2019). "•TLR9 ablation attenuates myocardial ischemia/reperfusion injury and inflammation." (PMID 31160091, 2019). "Also, TLR9-signaling seems to be nodal in experimental viral myocarditis, and activation of cardiac TLR9 prior to cardiac ischemia and reperfusion has been shown to limit subsequent myocardial damage and improve cardiac function." (PMID 25126740, 2014). "However, ablation of TLR9 in mice attenuates myocardial ischemia injury." (PMID 33138323, 2020). "TLR9 could be a therapeutic target to reduce myocardial ischemia/reperfusion injury." (PMID 31160091, 2019). "The TLR9–IFN-I-mediated inflammatory response contributes significantly to both ischemic and post-ischemic myocardial ischemia-reperfusion injury." (PMID 36081846, 2022). "Taken together, TLR2, TLR9, TNF-α and IL-10 were still elevated above control at the onset of cardiac ischemia." (PMID 23929312, 2013). "However, the role of TLR7 in myocardial ischemia and IRI may be less significant than TLR9 given that IS in TLR9−/− mice did not change with administration of HCQ." (PMID 36081846, 2022).
Alzheimer disease (8 papers, 2013 to 2024). A progressive, neurodegenerative disease characterized by loss of function and death of nerve cells in several areas of the brain leading to loss of cognitive function such as memory and language. "Recently, a novel TLR9 signaling pathway has been uncovered, which is functionally associated with the immune inflammatory response and reducing Aβ burden in Alzheimer’s disease (AD) mice." (PMID 23957925, 2013). "In macrophages, curli amyloid fibrils associate with DNA from damaged cells and activate intracellular TLR9 via toll-like receptor 3–mediated uptake, initiating an inflammatory response in Alzheimer's disease." (PMID 34048712, 2021). "TLR9-dependent trafficking of AMPA receptors may contribute to Alzheimer's disease." (PMID 38354781, 2024). "Here again, both beneficial and detrimental roles were attributed to TLRs and for instance TLR7, TLR8 and TLR9 signaling could enhance microglial amyloid beta uptake in the early stage of Alzheimer’s disease, but over time contribute to sustained neuroinflammation." (PMID 34335238, 2021). "This study is focused on the potential roles of various TLRs in various neurodegenerative diseases such as Parkinson’s disease (PD) and Alzheimer’s disease (AD), namely TLR2, TLR3, TLR4, TLR7, and TLR9 in AD and PD in human beings and a mouse model." (PMID 34827372, 2021).
bladder cancer (8 papers, 2019 to 2026). "Similarly, the TLR agonist Bacillus Calmette-Guérin is used for the local treatment of bladder cancer and clinical trials showed treatment efficacy of intratumoral injections with TLR9 agonists." (PMID 36913398, 2023). "Previously, expression of both TLR4 and TLR9 has been reported in human bladder cancer cells." (PMID 30358081, 2019). "Recently, imiquimod and TMX-202 (TLR7 agonists) were tested for bladder cancer immunotherapy, while CpG ODN (a TLR9 agonist) and HP-NAP (a TLR2 agonist) demonstrated reduced tumor growth in an MB49 bladder cancer mouse model." (PMID 38542078, 2024). "Previously, these BCG-derived products (BCG-CWS or BCG-derived DNA/RNA) were found to induce apoptosis in bladder cancer cells by activating TLR2, TLR4, TLR7, and TLR9 and thus inducing the myeloid differentiation primary response gene 88 (MYD88) pathway of extrinsic apoptosis." (PMID 36248858, 2022). "Next, we set out to assess whether STAT3 inhibition/TLR9 stimulation using CpG-STAT3ASO will prove effective alone or together with immune checkpoint blockade against genitourinary cancers, such as Renca and MB49 tumors, two commonly used models of mouse kidney and bladder cancers." (PMID 38259453, 2023).
Burkitt lymphoma (8 papers, 2013 to 2024). A rare form of malignant mature B-cell non-Hodgkin lymphoma. "This SNP has been recently reported to be linked with the Mutu-I and BJAB Burkitt lymphoma (BL), resulting in enhanced NF-κB activation upon TLR9 triggering." (PMID 37822929, 2023). "TLR9 has been shown to inhibit EBV lytic gene BZLF1 transcription through histone modification in Burkitt's lymphoma cells." (PMID 38537697, 2024). "The current study presents for the first time that EBV regulates TLR9 expression through m6A modification in human Burkitt's lymphoma cells." (PMID 38537697, 2024). "Noteworthy, similar results were obtained (data not shown) when the latter experiments were performed with Raji cells, a second Burkitt lymphoma line highly permissive to H-1PV and reported to express also elevated amounts of TLR-9 transcripts." (PMID 23383065, 2013). "Furthermore, it has been shown in our lab that triggering of TLR9 signaling in a Burkitt's lymphoma derived cell line blocks reactivation of EBV lytic cycle, reinforcing the risk of cell transformation." (PMID 28031537, 2017). "Importantly, whereas TLR9 was previously thought to be expressed only on immune cells, it has been shown that it also expressed on a number of different cancers (oral, prostate, breast, lung, Burkitt lymphoma), and signaling through TLR9 promotes proliferation and/or cell survival." (PMID 25452754, 2014). "To find out which kinases are most efficiently costimulated by BCR and TLR9 dual signals, first we performed a human phospho-MAPK protein array using a Burkitt's lymphoma cell line." (PMID 24801688, 2014).